IL10 (interleukin 10)
Diseases named in the same sentence as IL10 in open-access papers (continued):
Sharing a sentence is not in itself a finding about the gene and the disease.
infection (continued). "In the absence of infection, offspring of LFD- and HFD-fed dams exhibited significantly reduced serum levels of key cytokines involved in innate immunity, including G-CSF, GM-CSF, IL-6, and IL-10, compared to CD-fed dam offspring." (PMID 40766470, 2025). "Prior research supports this possibility: ethacridine lactate in wound models selectively inhibited IL-6 and IL-10 while boosting IL-12 and IFN-γ, effectively skewing the response toward a pro-inflammatory, infection-clearing profile without immunosuppressive effects." (PMID 41150817, 2025). "Additionally, in vivo and in vitro studies with S. mansoni soluble egg antigens (SEA), without the context of a full infection, showed that SEA can induce IL‐10 production in both mouse and human B cells, respectively." (PMID 40916477, 2025). "Notably, SDAV uniquely induced cytokines like IL-1 alpha, IL-10, IL-19, IL-23, and IL-28, which were not significantly elevated in MHV-JHM infection." (PMID 40358160, 2025). "We observed higher levels of IL-10 in samples with the highest levels of SCC (> 2,000,000 cells/mL) and this is like what observed in cattle: infection with either Gram positive or Gram negative bacteria resulted in release also of this anti-inflammatory cytokine." (PMID 41560862, 2025). "A second surprising finding was that while Tregs were present as expected from earlier T. congolense studies, they did not have an IL-10 regulatory signature, and the proportion of these cells in the total CD4+ T cell pool drastically decreased during the chronic stage of infection." (PMID 38535532, 2024). "This study utilized human cervical tissue explants as an infection model to demonstrate that GC inoculation increases the secretion levels of both the proinflammatory cytokines IL-1β and TNF-α and the antiinflammatory cytokines IL-10 but not TGF-β and IL-17A during the first 24 hours of infection." (PMID 39585777, 2024). "Compared to infection with untreated control and DNAseI-treated cultures of S. epidermidis 1457-M10, exogenously added chromosomal DNA had no significant impact on hMDM IL1B or IL10 expression." (PMID 39567551, 2024). "Interestingly, immunity conferred by LmexCen−/− was mediated mainly by a reduction in IL-4 and IL-10 levels rather than an increase in IFN-γ, thus enabling the control of infection and inhibiting disease development." (PMID 38543944, 2024). "In the clinical phase of FMDV infection, both cattle and swine cDCs are stimulated by the virus to produce IL-10, skewing the immune response towards a humoral rather than a T-cell mediated adaptive response, even when the FMDV infection of these cells is mostly abortive." (PMID 39340101, 2024). "In particular, the expression of IL13 and RETNLB was significantly increased in infected pigs, regardless of diet (main effect of infection with a fold change of 3.7 and 1.7, respectively), and the expression of CCL26, IL10 and TFF2 also tended to be increased." (PMID 38081984, 2023). "Cytokine signaling of IL-1β, IL-23, IL-17A, CCL7, CXCL10, TRAIL, CD40L, and BAFF provides protection against acute WNV infection in mice; IL-10 and IL-22 aid in WNV pathogenicity; IL-6 and IL-12 had no apparent effect during infection; and CCL2, TNF-α, and FasL roles remain elusive." (PMID 36992514, 2023). "Our findings showed that supplementing the rabbits with TQN significantly (p < 0.05) upregulated the transcription levels of IL-10, TLR-4, DEFB1 and TLR-2 genes comparing with the control non-supplemented rabbits at 96 h post-infection with P. multocida strain." (PMID 38292130, 2023). "Interestingly, low IL-10 levels were observed in the no-injection, sham-injection, and TMEV infection groups also exposed to PFOA." (PMID 37600798, 2023). "Thus, we evaluated the expression of two M1 genes (TNFα and CD86) and two M2 genes (IL-10 and CD206) at different time points post-infection under normoxic and hypoxic conditions in human and bovine macrophages." (PMID 36793725, 2023).
infection (continued). "Paradoxically, this enhancement of inflammatory cytokine production could also lead to increased production of IL-10 as a mechanism of negative feedback, which could consequently counteract BCG-mediated inflammation under infection in mice or humans in vivo." (PMID 38110948, 2023). "Interestingly, our data show that neither IL-10 nor PD-1 nor CD39 increase strongly in EC, who can control the infection spontaneously." (PMID 35529864, 2022). "Numbers and percentages of lymphocytes positive for RORγt were higher in the brains of IL10-/- mice compared to WT mice, and in CLN, there were significantly higher percents and numbers of RORγt+ cells on day five, but not day three, after infection." (PMID 36016413, 2022). "Thus, our data suggest that while IL-27 is present in the lungs at 60 days of infections, differences in IL-27 production are not responsible for differences in CD4 T cell and IL-10 expression between young and old stressed mice." (PMID 36189368, 2022). "Moreover, 60% to 90% of CD4+ or CD8+ EM T lymphocytes produced IL-10 and/or TGF-β1, with up to 40% of the cells producing TNF-α and IFN-γ, and no clear indication of immunological function after infection." (PMID 35720410, 2022). "In the absence of IL-10, P. chabaudi chabaudi (Pcc)-infected mice exhibit a reduction in survival preceded by an increase in IFN-γ and TNFα production during the first week of infection, as well as increased edema and hemorrhages in the brain by day 8 p.i.." (PMID 35631044, 2022). "Therefore, we monitored the levels of IL-6, IFN-γ, IL-2, IL-10, TGF-β, TNF-α, IL-12, and IL-17 in the lung lysates of M. tb-infected mice with and without L-GSH treatment at varying stages of the infection to assess the granulomatous response." (PMID 35453358, 2022). "The IL-10 responses generated by both CD8+ and CD4+ T cells were present within 1 month of infection in response to a mix of pp71 and US3 proteins, but not in response to latency associated proteins, despite IFNγ-specific responses being detected from early timepoints post infection." (PMID 36558866, 2022). "The frequency of intracellular IL-10 expressing CD4+ suppressive T cells to HBV core peptides was higher in HBV infected individuals with OBI (0.12%), CHB (0.11%), or resolved infection (0.1%), respectively, than in HBV non-infected individuals (0.06%) (P < 0.05)." (PMID 35464946, 2022). "In the MLN, infection induced a clear Th2 response, shown by increased expression of the Th2 master transcription factor GATA3 and the Th2 cytokines IL-5 and IL-13 in CD4+ CD44hi cells, and this response was not affected by the blockade of IL-10 signalling." (PMID 35428872, 2022). "Interestingly, IL-1β, IL-6, IL-10 and IL-12 were not significantly altered upon DAF depletion over the course of infection." (PMID 34197564, 2021). "However, the amount of p-STAT3 at 24 h was similar in NK cells from B6 and B6.Il10−/− mice, indicating that STAT3 activation occurs in NK cells at 24 h and 72 h post-infection, but that early activation is independent of IL-10 production." (PMID 35053151, 2021). "Moreover, the plasma levels of IL-2, IL-6, IL-8, IL-10, and TNF-α, observed in severe infection, are prominently greater than those with nonsevere infection." (PMID 34844296, 2021). "Our results show that IL-4, IL-6, IL-8, IL-10, IL-12P70, IL-1β, IL-2, IFN-γ, TNF-α, TNF-β and IL-17A are in the lungs The expression level of bacterially infected individuals was higher than that of patients without any infections (P<0.05)." (PMID 34925324, 2021). "As with infection with THP-1 macrophages, NuLi-1 cells infected with chronic P. aeruginosa isolates induced less IL-1β expression but more IL-6 expression, while the expression of TNF and IL-10 were undetectable (data not shown)." (PMID 33664232, 2021).
infection (continued). "In addition, we found that IL-6 and IL-10 levels, rather than viral load and neutralizing antibody titers, in patients with an SFTSV infection strongly correlated with outcomes (for severe disease with an ultimate outcome of recovery or death)." (PMID 34484214, 2021). "Here, we show that IL-10 overexpression only before the onset of the T cell response impaired control of M. tuberculosis growth; during chronic infection, IL-10 overexpression reduced the CD4+ T cell response without affecting the outcome of infection." (PMID 34554927, 2021). "falciparum-specific IL-10 producing CD4+ T cells but not with IFNγ or TNFα producing CD4+ cells; however, these cells could not prevent infection prospectively." (PMID 34414129, 2021). "Blimp-1 plays a larger role in longer infection, as only untreated infected Blimp-1 TKO (NTx), but not treated, had fewer IFN-γ+IL-21- with a concomitant increase in hybrid IFN-γ+IL-21+, supporting its role in IL-10 expression." (PMID 32634740, 2020). "IL-10 levels in the bronchiolar lavage fluid (BALF) and serum of mice infected with the capsulated strain were significantly higher than those infected with the non-capsulated strain, and these mice died within 3 days of infection." (PMID 32425944, 2020). "Moreover, the plasma levels of IL-2, IL-6, IL-8, IL-10, and TNF-α, observed in severe infection, are prominently greater than those in nonsevere infection." (PMID 32299202, 2020). "On the other hand, the treatment of THP-1 cells with UCO-979C EPS previous to infection with H. pylori did not exert any effect on the levels of IFN-γ and IL-10, since the concentrations of both cytokines were not different from the control infected THP-1 cells." (PMID 32230910, 2020). "However, the anti-inflammatory factor IL-10 expression was observably up-regulated (P < 0.01),while the expression of TNF-α was not significantly different between the two groups after infection with APEC." (PMID 33134350, 2020). "Infection of WT mice with Δhly resulted in significant levels of IL-10, but unlike in BMMs Δhly also induced significant amounts of IL-10 in TLR2-/- mice, suggesting that bacterial lipoproteins were not the dominant IL-10-inducing molecules in mice." (PMID 32634175, 2020). "At three months post-infection with low dose EBV, serum levels were biased towards proinflammatory cytokines and chemokines like TNFα, IL-8, and IL-6, while IFNγ and IL-10 were not significantly elevated, in contrast to what we observed after five weeks of high dose EBV infection." (PMID 31145756, 2019). "Similarly, at day 84 post-infection, no clear difference was observed in the concentration of IFN-γ, IL-1β, TNF-α, IL-12, IL-6, IL-10 and IL-4 in the both groups of mice." (PMID 31801478, 2019). "In addition, we did not observe any secretion of IL-2, IL-10, IL-13, and IL-6 during an AIC infection." (PMID 31801841, 2019). "We can advance a plausible explanation for the difference observed in a previous study where IL-10 signaling was no longer dominant beyond 6 hpi, namely, that frozen aliquots of MAP were used in divergent studies for in vitro infection, as opposed to the live MAP used in our study." (PMID 31969876, 2019). "In addition, the relative level of several cytokines such as IL-5, IL-10, IL-7, IL-13 and Basic-FGF was not as impacted by the infection as the other chemokines/cytokines." (PMID 31391513, 2019). "Furthermore, nitric oxide (NO) production was modulated by IL10 during AF2122/97 infection, but not at the nitric oxide synthase 2 (NOS2) mRNA level, as observed during G18 infection." (PMID 31527895, 2019). "Individuals coinfected with both HIV and S. japonicum had similar results when compared with people with no infection with HIV and S. japonicum; however, they had no higher levels of IFN-γ or IL-10 compared with individuals infected with HIV or S. japonicum alone." (PMID 30057918, 2018).
infection (continued). "On a systemic level (plasma) 12 h post-infection IL-6, IL-10, and MCP-1 was higher in TFPI-2−/− mice and no significant changes were observed in INF-γ, TNFα, and IL-12p70, whereas in BALF fluid, IL-10, and MCP-1 was higher in TFPI-2−/− mice." (PMID 30254643, 2018). "Meanwhile, ΔGntR infection increased the levels of IFN-γ, IL-1β, and TNF-α, indicating ΔGntR could induce the secretion of inflammatory but not anti-inflammatory cytokines IL-10." (PMID 29435171, 2018). "However, TNF‐α:IL‐10 ratios in individual serum samples were significantly lower in HFD compared to ND mice at 8 weeks post‐infection, primarily due to reduced levels of TNF‐α, and not increased IL‐10 abundance." (PMID 27794208, 2017). "Pretreatment of the infected rat models with doses of the traditional energy tonic (100 and 20 mg/mL/kg body weight) before infection nonsignificantly increased cytokines secretion (IL-1β, IL-2, IL-10, IL-13, IFN-γ, and RANTES), while others did not change when compared to those with infection only." (PMID 28408939, 2017). "Finally, those pigs euthanized after challenge with the highest levels of viremia and IL-10 (pigs A4, A5, C4 and F5, but not C5), also displayed a high increase of IFNγ in serum before death that may be interpreted as a failed last attempt of immune system for controlling last stages of infection." (PMID 27908827, 2017). "However, macrophages co-cultured with or without DTA-1 produced similar amounts of IL-12p40 and IL-10 against different MOI of T. gondii tachyzoites, ruling out its probable role in enhanced immunity against the infection upon in vivo activation of GITR." (PMID 27027302, 2016). "FoxO3a−/− macrophages secreted higher levels of IL-10 and reduced levels of IL-12 and TNF following infection with ST that does not express OVA, indicating that the impaired proinflammatory response observed in the absence of FoxO3a was independent of OVA expression and secretion." (PMID 27599659, 2016). "The current study also identifies several factors, including IL-1α, MIP-1α, RANTES, IL-12(p40) and IL-12(p70) that are induced in aged mice but not young mice following infection (compared to PBS) and other factors, including IL-1β, IL-10, IL-13 and eotaxin that are specific to young mice." (PMID 27936166, 2016). "Finally, we examined the molecular pathways responsible for instruction and/or maintenance of IL-10 expression by parasite-specific CD4+ IFN-γ+ T cells in the different lymphoid and nonlymphoid compartments during infection." (PMID 26459508, 2016). "Thus, although IL-10/PDL1 producing iregDC are the main DC subset infected, their infection is not required for induction of the immunosuppressive program." (PMID 26808628, 2016). "We found not only that IL-27 instructs IL-10 expression by CD4+ IFN-γ+ T cells within the spleen during malaria infection, as previously shown, but also that it controls IL-10 production by CD4+ T cells in nonlymphoid tissues during infection." (PMID 26459508, 2016). "Indeed, it would be unexpected for Ag-experienced, including parasite-specific, memory CD4+ T cells to continue to produce IL-10, or any nonhomeostatic cytokine, in the absence of inflammation and TCR signals after infection." (PMID 27630165, 2016). "However, monocyte-derived dendritic cells do not secrete proinflammatory cytokines of TNF-α, IL1β, IL6, IL10, or IL2, IFN-γ, or IL12 after infection with Ebola virus, though there are higher levels of certain chemokines (notably IL8 and MCP1)." (PMID 25592846, 2015). "Furthermore, tTreg contributed proportionally less IL-10 relative to other CD4+ cell types in 4x skin, and their number was not significantly different between the two infection groups." (PMID 25974019, 2015).
infection (continued). "Conversely, 15 days after treatment of blood stage infection with chloroquine, splenocytes showed spontaneous in vitro expression of TNFα, IL2, IL6, IL10, and IL12, but not IFNγ, and stimulation with P. falciparum pRBC blocked the expression of all these cytokines." (PMID 25890318, 2015). "Thus, CD200R was expressed during infection but was not significantly upregulated in response to MCMV, by either an IL-10-dependent or independent mechanism." (PMID 25654642, 2015). "In addition, mice infected with the lethal P. yoelii XL17 show higher levels of IL-10 and TGF-β compared to mice infected with the nonlethal strain P. yoelii XNL, at early time points during infection." (PMID 25276830, 2014). "The examination of mRNA transcripts in liver cells 24 h after infection confirmed fold variation increases of 5.8 and 4.8 times on average for IL-1 and COX-2, respectively, in P1G10 pretreated mice but not for TNF-α, IL-10, γ-IFN and iNOS, for which the results were comparable to untreated animals." (PMID 24757289, 2014). "Heat-inactivated DENV failed to induce IL-10 production in THP-1 cells, whereas ultraviolet-inactivated DENV induced IL-10 normally, indicating the essential role of structural proteins for this aspect of infection." (PMID 25412261, 2014). "Interestingly, we observed that prostaglandin inhibition reduced IL-10 and increased IFN-γ production at 2 days after infection and that IL-12 production was not altered at any time evaluated." (PMID 23818746, 2013). "In this study, the IL-10/TNF-alpha ratio in macrophages within this short time period may not be relevant to the outcome in mouse and human infection." (PMID 24130911, 2013). "Trends for increased IL-4/-13 and IL-10 production (n.s.)were detected in ileum as well as cecum tissue whereas IL-12, IFN-γ and TGF-β expression were detected at similar levels, irrespective of the infection status (data not shown)." (PMID 24040152, 2013). "Thus, even though CD11c+ cells contribute substantially to the early overall IL-10 production during LCMV infection, CD11c+ cell derived IL-10 does not seem to play a role for the outcome of the infection and the quality of the antiviral T cell response." (PMID 24244162, 2013). "In contrast, following infection of C57BL/6 mice with the L. major strain NIH/Sd, which produces nonhealing dermal lesions in a Th1-polarized setting, it was shown that IL-10-producing CD4+ CD25− FoxP3− Th1 cells rather than Treg cells are the major contributors to immune suppression." (PMID 23825956, 2013). "Thus, cell cultures established from spleens and the draining lymph node of the secondary site of infection produced high levels of parasite-specific IFN-γ in the absence of IL-4 and IL-10 cytokine production." (PMID 23554800, 2013). "Strikingly, IL-6, IL-1β, IL-1α, IL-10, MIP-1α, and KC (data not shown) were secreted at significantly higher levels in response to infection with C. caviae compared to C. muridarum, whereas G-CSF (data not shown), GM-CSF (data not shown), and TNF-α levels were similar between the strains." (PMID 22292031, 2012). "There was no induction of IL-10, MCP-1 or IFN-γ secretion by DCs after infection by either strain." (PMID 22911706, 2012). "Interestingly, the prevalence of high IL-10 mRNA was also greater in OSCC patients with HPV16, HPV18, and HPV16/18 infections than without HPV16, HPV18, and HPV16/18 infections." (PMID 23118878, 2012). "In women with P. falciparum, however, both comparative and longitudinal assessments consistently showed that the levels of IL-10 and IP-10 increased significantly whilst that of RANTES decreased significantly, regardless of gestational age at the time the infection was detected." (PMID 23155405, 2012). "No relevant IL-4 or IL-10 responses were found in the DLN, as the levels of these cytokines mRNA, in both non-immunized and BCG-immunized mice, were low and did not vary throughout the infection period." (PMID 22413022, 2012).